RIPK1 (receptor interacting serine/threonine kinase 1)
Diseases named in the same sentence as RIPK1 in open-access papers (continued):
Sharing a sentence is not in itself a finding about the gene and the disease.
Krabbe disease (2 papers, 2021 to 2022). A lysosomal disorder that affects the white matter of the central and peripheral nervous systems. "To understand the possible engagement of Ripk1 in inflammatory responses associated with Krabbe disease, we evaluated the dynamic expression of these cytokines in the spinal cord of twi-2J by RT-qPCR at three distinct stages of disease." (PMID 34172992, 2021). "Overall the findings show that expression of Ripk1 associates closely with the severity and progression of demyelination and gliosis in Krabbe disease, modelled in the twitcher strains." (PMID 34172992, 2021). "In a mouse model of Krabbe disease, an increase in RIPK1 expression in microglial cells and activation of cascades controlled by it, which lead to neuroinflammation, were found." (PMID 36778591, 2022). "The finding by Vitner and colleagues, that Ripk1 abnormal expression appeared to be specific to Gaucher and Krabbe diseases was of great interest, as these two disorders share pathological features that are distinct from other sphingolipidoses." (PMID 34172992, 2021). "As a first step towards understanding the relative Ripk1 functions in Krabbe disease, we intercrossed twitcher with the K45A kinase-dead Ripk1 mouse to homozygosity." (PMID 34172992, 2021). "We thus conclude that Ripk1 abundance correlates with disease severity and progression in mouse models of Krabbe disease." (PMID 34172992, 2021). "To clarify the role of Ripk1 in the pathogenesis of Krabbe disease, we first explored the contribution of its kinase function, by intercrossing twitcher and the K45A kinase-dead Ripk1 mouse and breeding to homozygosity." (PMID 34172992, 2021). "We next compared expression of Ripk1 in two distinct murine models of Krabbe disease." (PMID 34172992, 2021). "Given the complex and tight cellular regulation of Ripk1 expression, we contend that the marked Ripk1 upregulation in activated macrophage/microglia here noted in experimental Krabbe disease is likely to reflect as yet ill-understood but pathologically important biological processes." (PMID 34172992, 2021). "Rather, given the decisive contribution of Ripk1 to the molecular pathogenesis of several other diseases, the current findings clearly implicate an active role for this central mediator of cell death and inflammation in the florid neuropathology of Krabbe disease." (PMID 34172992, 2021). "One possible explanation is that in Krabbe disease the autophagosmal/lysosomal system is inherently defective due to deficiency of Galc, and in this context the negative contribution of Ripk1 kinase function might not be discernible." (PMID 34172992, 2021). "As described, the natural course of disease was unaffected and it was clear that the kinase activity of Ripk1 neither impacts development of Krabbe disease in this model, nor its relentless progression." (PMID 34172992, 2021). "Abnormal expression of these molecules was likewise identified in the mouse model of SD, indicating that Ripk1-related processes are not unique to Gaucher and Krabbe diseases and are more likely shared with other neurodegenerative sphingolipidoses." (PMID 34172992, 2021). "We conclude that Ripk1 kinase-dependent inflammatory and degenerative capabilities play no instrumental role in Krabbe disease; however, putative kinase-independent functions of Ripk1 remain formally to be explored in its molecular pathogenesis." (PMID 34172992, 2021).
nasopharyngeal carcinoma (2 papers, 2018 to 2024). A carcinoma arising from the nasopharyngeal epithelium. "Shikonin functions mainly through RIPK1 in the PANC-1 cell line and has no obvious effect on RIPK3; however, in AsPC-1 cells, it targets RIPK3 to induce cell necroptosis, and in nasopharyngeal carcinoma, shikonin upregulates both RIPK1 and RIPK3 expression and MLKL expression to promote necroptosis." (PMID 39584140, 2024).
osteonecrosis (2 papers, 2023 to 2025). A none disease characterized by death of bone tissue due to a lack of blood supply. "However, the beneficial effects of GSK2656157 may, in part, be due to inhibition of receptor-interacting protein kinase 1 (RIPK1), which has been implicated in the pathology of osteonecrosis." (PMID 37243756, 2023).
Osteopenia (2 papers, 2021 to 2022). Osteopenia is a term to define bone density that is not normal but also not as low as osteoporosis. "However, it remains unclear whether blocking RIPK1 kinase by necrostatin-1 could repair the damage caused by alcohol-induced osteopenia." (PMID 34745415, 2021). "Collectively, we demonstrated that chronic high-dose alcohol consumption induces osteopenia via necroptosis and thereby discovered that RIPK1 kinase may be a therapeutic target for alcohol-induced osteopenia." (PMID 34745415, 2021). "Collectively, we demonstrated that chronic high-dose alcohol consumption induced osteopenia via osteoblast necroptosis and revealed that RIPK1 kinase may be a therapeutic target for alcohol-induced osteopenia." (PMID 34745415, 2021). "However, it remains unknown whether RIPK1 mediates damage via activation of necroptosis in an alcohol-induced osteopenia model and the effect of necrostatin-1 on osteopenia requires further elucidation." (PMID 34745415, 2021). "Therefore, RIPK1 kinase and targeted antioxidants may be therapeutic targets for alcohol-induced osteopenia." (PMID 34745415, 2021). "A key inhibitor of RIPK1 kinase in the necroptosis pathway, necrostatin-1 (Nec-1), inhibits RIPK1/RIPK3/MLKL signaling, and thus might inhibit alcohol-induced osteopenia through decreased activation of osteoblast necroptosis." (PMID 36339402, 2022).
periodic fever syndrome (2 papers, 2020 to 2021). Fevers of unknown etiology recurring over months or years. "Noncleavable variants of RIPK1 are detrimental in humans, and heterozygous mutations cause an early-onset periodic fever syndrome and severe intermittent lymphadenopathy." (PMID 34437534, 2021).
periodontal disease (2 papers, 2019 to 2023). "These contradictory data indicated that alternative or RIPK1-independent necroptosis plays a critical role in the development of periodontal disease." (PMID 30814594, 2019). "Therefore, periodontal disease can be described as a RIPK-1 independent factor to gingival damages." (PMID 37266108, 2023).
plaque psoriasis (2 papers, 2020 to 2021). "GSK2982772, a RIPK1 inhibitor under development for the treatment of plaque psoriasis, has been dosed BID or TID in clinical trials as an IR formulation." (PMID 34136987, 2021). "GSK2982772 is a highly selective receptor-interacting protein kinase-1 (RIPK1) inhibitor being developed for the treatment of plaque psoriasis and other inflammatory diseases." (PMID 34136987, 2021). "RIPK1 was highly expressed in the epidermal basal layer, although its expression decreased significantly in the skin lesions of psoriasis vulgaris." (PMID 33077863, 2020).
renal carcinoma (2 papers, 2015 to 2022). A carcinoma arising from the epithelium of the renal parenchyma or the renal pelvis. "The combination of an mTOR and lysosomal inhibitor results in RIPK1- and oxidative stress-dependent necroptosis in human renal carcinoma cell lines, suggesting that autophagy may inhibit necroptosis via the degradation of RIPK1 and decreasing reactive oxygen species (ROS)." (PMID 25257169, 2015).
retinitis pigmentosa (2 papers, 2016 to 2019). Retinitis pigmentosa (RP) is an inherited retinal dystrophy leading to progressive loss of the photoreceptors and retinal pigment epithelium and resulting in blindness usually after several decades. "Given that RIPK1 and CASP8 take part in the defense of homeostasis downstream of many cytokine receptors, it is possible that inflammatory signals such as TNF contribute to the onset and progression of retinitis pigmentosa due to aberrant activation of RIPK1-dependent cell death." (PMID 26960254, 2016).
soft tissue sarcoma (2 papers, 2020 to 2023). A malignant neoplasm arising from muscle tissue, adipose tissue, blood vessels, fibrous tissue, or other supportive tissues excluding the bones. "Here, we report the first pre‐clinical application of an in vivo treatment protocol for soft‐tissue sarcoma that directly engages RIPK1‐mediated immunogenic cell death." (PMID 32419365, 2020). "This study focusses on the possibility to engage RIPK1‐mediated immunogenic cell death for the treatment of soft tissue sarcomas that occur at limb extremities." (PMID 32419365, 2020).
spinal cord injury (2 papers, 2018 to 2026). Penetrating and non-penetrating injuries to the spinal cord resulting from traumatic external forces (e.g., WOUNDS, GUNSHOT; WHIPLASH INJURIES; etc.). "Necroptosis, a regulated necrosis pathway mediated by the receptor-interacting protein kinases 1 and 3 (RIPK1 and RIPK3), is induced following spinal cord injury (SCI) and thought to contribute to neuronal and glial cell death." (PMID 29686269, 2018).
tauopathies (2 papers, 2021 to 2024). "The data obtained from two different murine models of tauopathy clearly indicate that the pathological process associated with TAU leads to an increase in RIPK1 mRNA expression levels." (PMID 39931431, 2024). "Our findings show elevated levels of RIPK1 mRNA levels across various forms of tauopathies, in both mouse models and human tissue samples associated with primary and secondary TAU-related disorders." (PMID 39931431, 2024). "Our data provide new insight into the mechanism by which the TAU protein induces a common RIPK1 pathway in different tauopathies." (PMID 39931431, 2024). "Apart from the neurodegenerative process, tauopathies are also characterized by a chronic low-grade neuroinflammation process, where the receptor-interacting protein kinase 1 (RIPK1) protein plays an essential role." (PMID 39931431, 2024). "The encouraging findings from our initial research prompted us to investigate the potential anti-inflammatory and/or neuroprotective properties of a RIPK1 inhibitor called GSK2982772 in our AAV- TAUP301L -based tauopathy model." (PMID 39931431, 2024). "However, the fact that PSP patients, a neuroglial 4R tauopathy, also exhibit elevated RIPK1 levels suggests a more direct role of TAU involvement." (PMID 39931431, 2024). "The observation of an increase in RIPK1 levels in these tauopathies led us to explore whether its modulation could serve as a therapeutic target to first inhibit neuroinflammation and subsequently slow neurodegeneration." (PMID 39931431, 2024). "Our research aimed to explore the role of RIPK1 in various tauopathies." (PMID 39931431, 2024). "However, the implication of RIPK1 associated with TAU or TAU neurofibrillary tangles is unknown, although it is well known that glial contribution is critical for tauopathies." (PMID 39931431, 2024). "The targets of 414 include kinases involved in tauopathy pathogenesis, including protein kinase R-like endoplasmic reticulum kinase or PERK, the mitogen-activated protein kinase, or MAPK, cascade, receptor-interacting serine/threonine-protein kinase 1 or RIPK1 and the receptor tyrosine kinase, KIT." (PMID 33530349, 2021). "Although a previous study had already reported elevated RIPK1 levels in AD patients, since this disease is a secondary tauopathy underlying APP amyloidosis, it could not be confirmed that this increase in RIPK1 levels was a direct consequence of TAU hyperphosphorylation and aggregation." (PMID 39931431, 2024). "Finally, to assess the relevance of RIPK1 in human TAU pathology, we analyzed post-mortem hippocampal biopsies from four asymptomatic control donors, four AD patients with neurofibrillary tangles (a secondary tauopathy), and five patients with PSP, a 4R-tauopathy." (PMID 39931431, 2024).
varicocele (2 papers, 2023 to 2024). A condition characterized by the dilated tortuous veins of the spermatic cord with a marked left-sided predominance. "For example, varicocele, which causes male infertility, seriously affects semen quality, and the expression of RIPK1 and RIPK3 in the sperm of varicocele patients was significantly increased compared to a control group." (PMID 38762505, 2024). "RIPK1, RIPK3, GSDME and HSP 90 were increased in bilateral varicocele group." (PMID 36819092, 2023). "In our study, we found that RIPK1, RIPK3 and HSP 90 were activated in bilateral varicocele group." (PMID 36819092, 2023).
Venous thrombosis (2 papers, 2018 to 2020). Formation of a blood clot (thrombus) inside a vein, causing the obstruction of blood flow. "Those that have been performed, however, suggest an important role of the RIPK1/RIPK3/MLKL driven necroptosis pathway in venous thrombosis." (PMID 33142926, 2020). "Given the ready availability of inhibitors of RIPK1/RIPK3 and the large clinical impact of venous thrombosis annually worldwide, the mechanistic relationship between RIPK1/RIPK3/MLKL, platelets, NETosis and venous thrombosis certainly merits further investigation." (PMID 33142926, 2020).
viral hepatitis (2 papers, 2019 to 2020). An acute or chronic inflammation of the liver parenchyma caused by viruses. "More recently, studies examining the role of RIPK1 in a viral hepatitis model using murine hepatitis virus type 3 (MHV3) have found that parenchymal cell deficiency of RIPK1, RIPK1LPC-KO, sensitizes mice to apoptosis from MHV3 and PAMPs such as poly I:C." (PMID 33353156, 2020). "The present study aimed to define the role of RIPK1 in hepatocytes during fulminant viral hepatitis, a worldwide syndrome mainly observed in hepatitis B virus (HBV) infected patients." (PMID 30622241, 2019). "We first investigated the potential functions that RIPK1 could play in liver parenchymal cells during fulminant viral hepatitis by taking advantage of a physiological murine model based on MHV3 infection." (PMID 30622241, 2019). "In the present study, we now investigate the unknown role of RIPK1 during the specific circumstances of fulminant viral hepatitis." (PMID 30622241, 2019).
abscess (1 paper, 2024). An inflammatory process characterized by the accumulation of pus within a newly formed tissue cavity which is the result of a bacterial, fungal, or parasitic infection or the presence of a foreign body. "The examination of the IgE-CAI skin lesion of Ccr2−/− mice illustrated the functional consequence of the failure in the generation of CMDMs, namely the appearance of abscess-like clusters of TUNEL and RIPK1 double-positive neutrophils." (PMID 38396021, 2024).
adenosquamous carcinoma (1 paper, 2023). A carcinoma composed of malignant glandular cells and malignant squamous cells. "Differences in expression of RIPK1, RIPK3, and pMLKL were examined by comparing the immunoreactive score (IRS) in the groups of histological subtypes (squamous cell carcinoma, adenocarcinoma, adenosquamous carcinoma), grading (G1-G3), TNM- and FIGO-classification." (PMID 37197430, 2023).
alcoholic cirrhosis (1 paper, 2018). "Alcoholic cirrhosis is associated with necrotic hepatocyte cell death, called necroptosis, which is regulated by RIP1-RIP3-MLKL- (mixed lineage kinase domain-like protein-) mediated necrotic cascade, but the role of RIPK1 and RIPK3 in the pathogeneses of alcoholic liver cirrhosis is largely unknown." (PMID 30596105, 2018). "Our study showed that RIPK3 but not RIPK1 was activated in patients with alcoholic cirrhosis." (PMID 30596105, 2018). "Very strong RIPK3 staining but not RIPK1 was found in the necrotic area, indicating that RIPK3, but not RIPK1, was involved in alcoholic liver cirrhosis, consistent with previous studies showing RIPK3 is mediated in the mouse model of ethanol-induced liver injury and progression of ALD patients." (PMID 30596105, 2018).
Allergy (1 paper, 2022). An allergy is an immune response or reaction to substances that are usually not harmful. "RIPK-1, a key mediator of this complex, is rapidly phosphorylated upon allergen exposure, thereby activating caspase 8, which appears to mediate a functional shift of the ripoptosome from a ‘cell death’ state to an ‘allergy’ state by promoting rapid degradation of RIPK-1." (PMID 34992274, 2022).
alopecia (1 paper, 2024). Hair loss usually from the scalp. "IkkeK38A/K38ATbk1fl/D135NK14-Crewt/tg mice did not develop alopecia, showing that combined inhibition of IKKε and TBK1 kinase activity caused RIPK1 kinase-dependent transient hair loss by a non-keratinocyte-intrinsic mechanism." (PMID 38167258, 2024).
alopecia areata (1 paper, 2025). Loss of scalp and body hair involving microscopically inflammatory patchy areas. "Here, we first investigated the involvement of RIPK1 in alopecia areata (AA)." (PMID 40004031, 2025).
ataxia telangiectasia (1 paper, 2024). Ataxia-telangiectasia is the association of severe combined immunodeficiency (affecting mainly the humoral immune response) with progressive cerebellar ataxia. "FCM findings provided informative clues, although they lacked specificity for diagnosing hypomorphic V(D)J recombination defects, Ataxia Telangiectasia, CVID, LRBA deficiency, RIPK1 deficiency, and Good’s syndrome." (PMID 39072316, 2024).
Atrophy (1 paper, 2025). Any weakening or degeneration, especially through lack of use. "Apoptosis in PT cells results in tubular atrophy with loss of kidney function, and necroptosis participates in the pathogenesis of DKD via the ubiquitin C-terminal hydrolase L1 (UCHL1)-RIPK1/RIPK3 pathway." (PMID 40722167, 2025).
autoimmune enteropathy (1 paper, 2025). Severe-immune mediated enteropathy describes a variety of intestinal disorders that can range from a serious, early-onset systemic disease (IPEX) to a mild isolated gastrointestinal disease. "The pathology of celiac disease and autoimmune enteropathy primarily manifests in the proximal small intestine, conditions where RIPK1-mediated immune regulation could play a pivotal role in modulating inflammatory responses and maintaining intestinal homeostasis." (PMID 40307618, 2025).
autoimmune hepatitis (1 paper, 2021). Hepatitis caused by autoantibodies. "Of concern, was the observation that in concanavalin A (ConA)-induced autoimmune hepatitis, RIPK3 deletion was protective, whereas RIPK1 inhibition exacerbated disease, accelerated animal death, and was associated with increased hepatocyte cell death." (PMID 34921136, 2021).
B-cell lymphomas (1 paper, 2023). "Therefore, we speculated that the down-regulation of RIPK1 may also play a pathogenic role in B-cell lymphomas." (PMID 37462822, 2023). "Taken together, our results indicated that RIPK1 is commonly down-regulated in B-cell lymphoma cells." (PMID 37462822, 2023). "Altogether, RIPK1 is a promising target for B-cell lymphoma treatment." (PMID 37462822, 2023). "Interestingly, we observed that RIPK1 mRNA levels were decreased in B-cell lymphoma cell lines when compared with GM12878 normal B-cells." (PMID 37462822, 2023). "Due to the down-regulation of RIPK1 expression of kinase activity promoting cell proliferation, we speculated that activation of RIPK1 by small molecules may lead to cell death of B-cell lymphoma." (PMID 37462822, 2023). "Taken together, we consider that RIPK1 may be a potential target in the clinical application of B-cell lymphoma (including CLL, DLBCL, and FL) treatment." (PMID 37462822, 2023). "More importantly, modifying RIPK1 kinase activity by a small molecule (such as necrostain-1, HOIPIN-1, etc.)alters the cell growth status of B-cell lymphoma, showing that RIPK1 exhibits anti-tumor activity in the context of B-cell lymphoma." (PMID 37462822, 2023).
behavioral disorders (1 paper, 2022). "RIPK1 inhibitor Nec-1s reduced the levels of apoptosis and cell necrosis, inflammatory responses, ROS production and mitochondrial dysfunction, and also reduced behavioral disorders in mice." (PMID 35054920, 2022).